TIMP1 (TIMP metallopeptidase inhibitor 1)
Diseases named in the same sentence as TIMP1 in open-access papers (continued):
Sharing a sentence is not in itself a finding about the gene and the disease.
laryngeal carcinoma (3 papers, 2014 to 2019). Carcinoma that arises from the laryngeal epithelium. "This study demonstrated for the first time the tissue expression and the concentrations of MMP-9 and TIMP-1 in serum and plasma in patients with laryngeal carcinoma." (PMID 31143300, 2019). "Studies report different TIMP-1 expression levels in laryngeal carcinoma." (PMID 31143300, 2019). "The aim of this study was to assess the expression of MMP-9 and TIMP-1 in cancerous tissue as well as in the serum and plasma concentrations of these proteins in patients with laryngeal cancer and compare the results to the inflammatory reaction in healthy subjects." (PMID 31143300, 2019). "The balance between the level of MMP-9 and TIMP-1 is disrupted in laryngeal cancer." (PMID 31143300, 2019). "The balance between the level of MMP-9 and TIMP-1 is disrupted in laryngeal carcinoma." (PMID 31143300, 2019). "The aim of this study was to assess the expression of MMP-9 and TIMP-1 in cancerous tissue as well as in serum and plasma concentrations of these proteins in patients with laryngeal cancer and compare the results to the inflammatory reaction in healthy subjects." (PMID 31143300, 2019).
Left ventricular diastolic dysfunction (3 papers, 2021 to 2023). Abnormal function of the left ventricule during left ventricular relaxation and filling. "Alterations in MMP9 and TIMP1 enzymes were found to be significant indicators of greater degrees of asymptomatic left ventricular diastolic dysfunction." (PMID 34957261, 2021).
mesothelioma (3 papers, 2000 to 2021). A usually malignant and aggressive neoplasm of the mesothelium which is often associated with exposure to asbestos. "In mesothelioma cells, among the angiogenesis-related proteins, angiopoietin-1, thrombospondin-1 (TSP-1), and tissue inhibitor of metalloproteinases-1 (TIMP-1) were significantly downregulated upon SDC-1 over-expression, whereas IL-8 was upregulated upon SDC-1 silencing." (PMID 33562126, 2021).
migraine (3 papers, 2012 to 2025). "TIMP-1 levels were lower in migraine patients; the MMP-9/TIMP-1 ratio was significantly higher." (PMID 41357008, 2025). "In patients suffering from migraine without aura, however, the ratio of MMP-9 to TIMP-1 was increased compared to patients with aura, reflecting a potential distinct pathophysiological mechanism." (PMID 22970361, 2012).
mucositis (3 papers, 2022 to 2025). Mucositis is inflammation and damage of the mucous membranes lining the mouth and other parts of the gastrointestinal (GI) tract. "The current study observed an upregulation of MMPs and a concomitant downregulation of TIMP-1 in response to 5-FU-induced mucositis." (PMID 40524059, 2025). "In comparison to the Control and ALA groups, 5-FU treatment enhanced MMP-1, MMP-2, MMP-8, and TIMP-1 activation in sera and tissues in the Mucositis + ALA group." (PMID 36290656, 2022). "MMP-1, MMP-2, MMP-8, and TIMP-1 activities in serum, stomach, small intestine, and large intestine were significantly higher in the Mucositis group in comparison to the Control and ALA groups (p < 0.05–0.0001)." (PMID 36290656, 2022). "The ability of VER to decrease MMP levels and increase the expression of TIMP-1 suggests a protective mechanism by maintaining the integrity of the extracellular matrix and reducing the hyperactivity of proteolytic enzymes that contribute to tissue damage in 5-FU-induced mucositis." (PMID 40524059, 2025). "The results revealed mucositis-elevated TNF-, IL-1, MDA, MMP-1, -2, -8, and TIMP-1 levels in both tissues and sera, and these values dropped dramatically following ALA treatment." (PMID 36290656, 2022).
myelofibrosis (3 papers, 2015 to 2021). A partial or complete replacement of the bone marrow stroma by fibrous tissue. "The level of TIMP-1 in myelofibrosis (MF) >1 group was significantly higher than that in MF ≤ 1 group." (PMID 34249954, 2021). "The author therefore believed that TIMP-1 played an important role in the pathogenesis of myelofibrosis." (PMID 34249954, 2021). "Also the ratio of total TIMP1/MMP9 was significantly higher in patients with Myelofibrosis compared with controls (P = 0.0004)." (PMID 25906101, 2015).
myocardial ischemia (3 papers, 2015 to 2020). A disorder of cardiac function caused by insufficient blood flow to the muscle tissue of the heart. "Timp1 is a natural inhibitor of Mmp9, and it plays a regulatory role in post-myocardial ischemia by accelerating myocardial remodeling." (PMID 33061247, 2020). "In the same study, we observed an increased MMP-9/TIMP-1 ratio and lower myofibroblast density in CB2 receptor-deficient mice in our in vivo model of myocardial ischemia." (PMID 26539497, 2015). "In our setup, following myocardial ischemia biglycan, decorin and Timp1 mRNA levels are increased in BC−/EC+." (PMID 25875863, 2015).
myopia (3 papers, 2020 to 2025). "The secretion of TIMP-1, MMP2, bFGF, and IGF-1, which were involved in pathological myopia, were detected with ELISA assay in ARPE-19 cells treated with 1 μg/mL of insulin for 24 or 72 h." (PMID 34001063, 2021). "The combination of bilberry extract and DHA demonstrates significant efficacy in controlling myopia progression through multiple mechanisms, including upregulation of Chrnb4 gene expression, modulation of the TGF-β/MMP-2/TIMP-1 signaling pathway, and enhancement of dopamine levels." (PMID 40534703, 2025).
pancreatitis (3 papers, 2018 to 2022). Inflammation of the pancreas. "Based on the results, apolipoprotein A-IV (APOA4), apolipoprotein C-III, IGFBP2 and tissue inhibitor of metalloproteinase 1 (TIMP1) were found significantly altered in the serum of PDAC patients (stage I–IV) compared to those with pancreatitis as well as healthy controls." (PMID 35216204, 2022). "Notably, herein the identified CCN2 + PLG+FN+Col4 + CA19.9 panel appeared to have a higher capability in discriminating PDAC from pancreatitis (AUC = 0.94) than the recently proposed TIMP1 + LRG1 + CA19.9 panel (AUC = 0.89)." (PMID 29941541, 2018).
parasitic infection (3 papers, 2012 to 2024). "For the first time, we provide evidence that the functions of soluble TIMP-1 extend beyond its established role in DC migration during parasitic infection, to include the modulation of DC-mediated presentation of tumor antigens to T cells." (PMID 38777826, 2024).
polyp (3 papers, 2015 to 2023). A usually exophytic mass attached to the underlying tissue by a broad base or a thin stalk. "In this study, we found a significant difference between control, polyp and cancer groups in terms of expression of TIMP-1 (p < 0.001)." (PMID 29201696, 2015). "Insufficient suppression of MMP‐9 by TIMP‐1 in polyp could lead to degradation of ECM, and hence, pseudocyst formation." (PMID 33900049, 2021). "The levels of TIMP-1, COX-2 and MMP-7 in cancer tissues were higher than those of both normal tissue and polyp tissue (p = 0.009 and p = 0.001; p < 0.001 and p < 0.001; p = 0.029 and p = 0.008, respectively)." (PMID 29201696, 2015). "The expressions of TIMP-1, COX-2 and MMP-7 levels were significantly higher in polyp tissue compared to normal tissue (p = 0.024, p < 0.001, p = 0.009, respectively)." (PMID 29201696, 2015). "The mean TIMP-1, COX-2 and MMP-7 levels were significantly higher in polyp tissue compared to normal tissue (p = 0.024, p < 0.001, p = 0.009, respectively)." (PMID 29201696, 2015). "The areas under the curve for TIMP-1, COX-2 and MMP-7 were determined to be 0.647, 0.689 and 0.639, respectively and were found to be statistically significant (p = 0.024, p = 0.003 and p = 0.032, respectively) in the polyp group." (PMID 29201696, 2015). "Expression of TIMP-1, COX-2 and MMP-7 in cancer tissues were higher than both normal tissue and polyp tissue (p = 0.009 and p = 0.001; p < 0.001 and p < 0.001; p = 0.029 and p = 0.008, respectively)." (PMID 29201696, 2015).
proliferative diabetic retinopathy (3 papers, 2015 to 2024). Advanced retinopathy due to diabetes mellitus characterized by the formation of new vessels in the retina. "Significant positive correlations between TIMP-1, MMP-9, and VEGF vitreous fluid levels in proliferative diabetic retinopathy were clinically confirmed." (PMID 33218057, 2020).
skin cancer (3 papers, 2014 to 2025). "In this study, we found that IL-32γ inhibited cancer sphere formation and its effect was associated with the downregulation of TIMP-1 expression in skin cancer cells." (PMID 30486830, 2018). "In GWAS analysis, we found that ITGAV and TIMP-1 were significantly associated with IL-32γ-inhibited skin tumor development." (PMID 30486830, 2018). "With the data analysis using a genome-wide association study (GWAS), we found that IL-32 was closely related to many cancers, and further analysis showed that IL-32 was closely associated with several genes including ITGAV and TIMP-1, which have been implicated in skin tumor development." (PMID 30486830, 2018). "The expression levels of CD44 and CD133 were decreased by knockdown of ITGAV and TIMP-1 in skin cancer cells compared to control cells." (PMID 30486830, 2018). "These facts correlated with our results revealing that IL-32γ suppressed cancer stemness through the inhibition of ITGAV and TIMP-1 in A431 and SK-Mel-28 skin cancer cells." (PMID 30486830, 2018). "Growing evidence has demonstrated that TIMP-1 expression is related to skin cancer progression." (PMID 30486830, 2018). "The combination of IL-32γ and NF-κB inhibitor, BAY, synergistically reduced TPA-induced epidermal hyperplasia, inflammation, and skin cancer sphere formation by further suppressing ITGAV and TIMP-1." (PMID 30486830, 2018). "In this study, the expression of IL-32γ resulted in reduced skin tumor development by downregulating ITGAV and TIMP-1 expression through the regulation of NF-κB signaling in IL-32γ mice." (PMID 30486830, 2018). "This study demonstrated the inhibitory effect of IL-32γ on skin tumor development by the downregulation of ITGAV and TIMP-1 via the NF-κB signaling." (PMID 30486830, 2018).
synovitis (3 papers, 2013 to 2025). Inflammation of a synovial membrane. "While, the relative mRNA expression of PLOD2, COL1A1, TIMP1, and TGF-β was significantly decreased in the synovitis ointment group." (PMID 35815270, 2022). "To verify the effects of synovitis ointment on bone cells fibrosis, through RT-PCR assays, we examined the relative mRNA expression of PLOD2, COL1A1, TIMP1, and TGF-β under different treatment conditions." (PMID 35815270, 2022). "Effects of synovitis ointment on bone cell fibrosis were detected through Masson staining, and the relative mRNA expression of PLOD2, COL1A1, TIMP1, and TGF-β was observed using the real-time quantitative (RT-PCR) method." (PMID 35815270, 2022). "As expected, synovitis ointment decreased the levels of PLOD2, COL1A1, TIMP1, and TGF-β." (PMID 35815270, 2022). "The levels of PLOD2, COL1A1, TIMP1, and TGF-β were significantly higher in those lacking drug treatments than those treated with synovitis ointment (P < 0.05)." (PMID 35815270, 2022).
systemic lupus erythematosus (3 papers, 2021 to 2025). An autoimmune multi-organ disease typically associated with vasculopathy and autoantibody production. "While studying patients with systemic lupus erythematosus (SLE) in patients that were sex- and age-matched with healthy volunteers’ serum levels of MMP-9 and TIMP-1 were determined, the same procedure was performed after CQ treatment." (PMID 34948342, 2021). "TIMP1 was primarily involved in chemokine signaling pathway, cytokine-cytokine receptor interaction, leishmania infection, NOD-like-receptor signaling pathway, systemic lupus erythematosus, TOLL-like-receptor signaling pathway." (PMID 37266443, 2023).
thymoma (3 papers, 2020 to 2023). A neoplasm arising from the epithelial cells of the thymus. "Extracellular TIMP-1 of thymoma may prevent invasion and metastasis mainly by inhibiting the remodelling of the extracellular matrix." (PMID 36991043, 2023). "In this study, the serum TIMP-1 of patients with thymoma was lower than that of normal controls." (PMID 36991043, 2023). "Based on the same PRM validation sample batch we also examined TSCC/thymoma marker candidates such as CNOT2/9, SHMT1, VCAN, HTRA1, and TIMP1 in parallel with CK19 in the PRM analysis (for raw fragment abundances of all PRM samples)." (PMID 31967407, 2020). "Further comparison of protein expression profiles between thymoma and TSCC identified several extracellular matrix (ECM) proteins, such as CFD, TIMP1, and VCAN, that are overexpressed in TSCC and involved in complement activation and inflammation process." (PMID 31967407, 2020). "Further comparison of type B3 and TSCC proteome revealed a number of differential proteins with similar expression patterns: CNOT2/9 and SHMT1 were found with high abundance in type B3 thymoma, while the abundance of HTRA1, TIMP1, and VCAN was higher in TSCC than in type B3 thymoma." (PMID 31967407, 2020).
thyroid tumor (3 papers, 1999 to 2023). A benign or malignant neoplasm affecting the thyroid gland. "However, TIMP-1 expression was not increased in NPA and SW579 cells, both of which are derived from poorly differentiated thyroid tumours." (PMID 10098765, 1999).
Varicose veins (3 papers, 2014 to 2017). Enlarged and tortuous veins. "Increased collagen content has been shown in varicose vein pathology, for this reason active collagenase MMP-1 was measured in the present study and we have calculated the active MMP-1/TIMP-1 and MMP-1/TIMP-2 ratios." (PMID 27362269, 2016). "Our results describe a decrease in active MMP-1, total MMP-2 (while total MMP-1 is not modified in varicose veins) and an increase in TIMP-1 and TIMP-2 concentrations in varicose veins." (PMID 24505358, 2014).
viral encephalitis (3 papers, 2013 to 2023). Encephalitis resulting from viral infection. "Although neither has been directly implicated in lymphocyte recruitment to the lungs, TIMP-1 does appear to regulate CD4+ T cell migration into brain parenchyma in a murine model of viral encephalitis, independently of MMPs." (PMID 26243260, 2015). "A high MMP-9/TIMP1 ratio in pediatric patients is closely tied to encephalitis and prolonged febrile seizures." (PMID 37365625, 2023). "In summary, our data demonstrate a novel MMP-independent role of TIMP-1 in regulating CD4+ T cell migration across the glia limitans during viral encephalitis." (PMID 24156369, 2013).
vitamin D deficiency (3 papers, 2013 to 2023). A nutritional condition produced by a deficiency of VITAMIN D in the diet, insufficient production of vitamin D in the skin, inadequate absorption of vitamin D from the diet, or abnormal conversion of vitamin D to its bioactive metabolites. "Based on the present study high levels of TNF-α and IL-6 as well as vitamin D deficiency in studied participants could disturb the MMP-9/TIMP-1 balance and lipid metabolism, leading to plaque formation/ rupture in predisposed CAD patients." (PMID 38357561, 2023). "The present study suggested that high levels of TNF-α and IL-6 and vitamin D deficiency in our studied patients could disturb the MMP-9/TIMP-1 balance and lipid metabolism, leading to plaque formation/ rupture in predisposed CAD patients." (PMID 38357561, 2023). "To begin to address putative mechanisms whereby vitamin D deficiency might contribute to our observed findings, we looked at enzymes associated with lung remodeling and at TIMP-1, a gene that we noted in early experiments to be altered by cigarette smoke." (PMID 23781205, 2013).
Achalasia (2 papers, 2015 to 2018). A disorder of esophageal motility characterized by the inability of the lower esophageal sphincter to relax during swallowing and by inadequate or lacking peristalsis in the lower half of the body of the esophagus. "Previously, MMP-9 and its inhibitor (tissue inhibitor of metalloproteinase-1 or TIMP-1) have been detected by immunohistochemistry in biopsies of achalasia patients." (PMID 30449890, 2018). "TIMP-1+ cell percentage was higher in achalasia patients compared with control group." (PMID 26078981, 2015). "Moreover, number of TIMP-1-producing cells in types II and III achalasia was higher when compared to type I achalasia." (PMID 26078981, 2015).
Acute encephalopathy (2 papers, 2018 to 2022). "Increased serum levels of MMP-9 and decreased levels of tissue inhibitor of metalloproteinase 1 (TIMP-1) were found in children who experienced acute encephalopathy following prolonged febrile seizures." (PMID 29531525, 2018).
adenomyosis (2 papers, 2022 to 2025). The growth of endometrial tissue inside the muscular wall of the uterine corpus. "This is in agreement with earlier transcriptomic studies where mRNA levels of TIMP1 showed higher expression in decidualized endometrial stromal cells of adenomyosis." (PMID 41272701, 2025). "On comparing adenomyosis patients with controls, significant differences were observed in the expression of MMP9, MMP11, SERPINA1, IGFBP5, and TIMP1 (p < 0.05); however, MMP7 and THBS1 remained comparable." (PMID 41272701, 2025).
amyloid (2 papers, 2023). "To determine if Timp1 can be used as a molecular signature of CD169+ perivascular macrophages associated with vascular amyloid after Aβ immunotherapy, we performed triple staining with Thio-S, CD169, and Timp1." (PMID 37649100, 2023).
and T-cell lymphomas (2 papers, 2013 to 2016). "MMP9 and TIMP1 expression is significantly upregulated in canine T-cell lymphomas, and was upregulated in both Ema and TL-1 cells." (PMID 27639374, 2016). "This same result was obtained also in vitro, as the T-cell lymphoma cell line (OSW) showed about 3-fold TIMP-1 mRNA higher amount than B-cell lymphoma cell line (CLBL-1)." (PMID 23641796, 2013). "Significantly higher MMP-9 and TIMP-1 mRNA expression levels were observed in T-cell lymphomas compared to B-cell lymphomas and healthy controls (p<0.05)." (PMID 23641796, 2013). "Significantly higher levels of TIMP-1 mRNA were observed in T-cell lymphomas compared to B-cell lymphomas and controls." (PMID 23641796, 2013). "Interestingly, higher MMP-9, MT1-MMP, VEGF-A, VEGF-164 and TIMP-1 mRNA expressions were observed in HG T-cell lymphomas compared to LG T-cell lymphomas, although the differences were not statistically significant." (PMID 23641796, 2013). "Overall, this experimental evidence supports the hypothesis that MMP-9 and TIMP-1 may act in concert in canine T-cell lymphoma." (PMID 23641796, 2013). "The same may hold true in dog where HG T-cell lymphomas showed a higher TIMP-1 mRNA expression than LG." (PMID 23641796, 2013). "MT1-MMP, TIMP-1 and RECK mRNA levels were significantly higher in T-cell lymphomas than in B-cell lymphomas." (PMID 23641796, 2013). "The expressions of MMP-9, MT1-MMP, TIMP-1 and RECK were significantly higher in HG T-cell lymphomas compared to HG B-cell lymphomas (p<0.05)." (PMID 23641796, 2013). "Moreover, MMP-9, MT1-MMP, TIMP-1 and VEGF-A were expressed at the highest levels in high-grade T-cell lymphomas." (PMID 23641796, 2013).
arterial disease (2 papers, 2006 to 2019). "Similar correlationsbetween serum TIMP-1 concentrations were observed by Tayebjeeet al, in patients with angiographically provenperipheral arterial disease, in which TIMP-1 concentration alsocorrelated with the severity of clinical symptoms." (PMID 16864898, 2006).
Ascites (2 papers, 2021). Accumulation of fluid in the peritoneal cavity (between the layers of the peritoneum that lines the abdomen). "Moreover, higher TIMP-1 concentrations correlated with larger volumes of ascites." (PMID 34572929, 2021). "The expression of TIMP-1 was highest, followed by TIMP-2 and then TIMP-3 in CN ascites." (PMID 35047406, 2021).